ATAD2 (ATPase family AAA domain containing 2)
Diseases named in the same sentence as ATAD2 in open-access papers (continued):
Sharing a sentence is not in itself a finding about the gene and the disease.
glioblastoma (5 papers, 2013 to 2026). The most malignant astrocytic tumor (WHO grade IV). "Further, ATAD2 exhibits the highest synergy with Myc signaling in glioblastoma (GBM), breast, and ovarian malignancies among the genes upregulated in the 8q24 chromosomal region." (PMID 41154392, 2025). "Results showed that elevated ATAD2 expression was noted in glioblastoma (GBM)." (PMID 41158756, 2026). "ATAD2, an ATPase domain-containing protein, is also known to upregulate PLK4 transcription, which was demonstrated in glioblastoma (GB) cells." (PMID 41488365, 2025). "Exogenous ATAD2 overexpression can significantly increase the expression of Polo-like kinase 4 (PLK4) to promote the occurrence and radiation resistance of glioblastoma (GBM), and so ATAD2 may be a key regulator of PLK4 transcription in GBM." (PMID 36008934, 2022).
osteosarcoma (5 papers, 2020 to 2022). A usually aggressive malignant bone-forming mesenchymal neoplasm, predominantly affecting adolescents and young adults. "Knockdown of METTL3 can suppress the proliferation, migration, and invasion of the human osteosarcoma cell lines SAOS-2 and MG63 by inhibiting the m6A methylation level and expression of the ATPase family AAA domain-containing protein 2 (ATAD2)." (PMID 34094986, 2021). "Moreover, the ATPase family AAA domain-containing protein 2 (ATAD2), identified as the downstream target of METTL3, contributes to its oncogenic role in osteosarcoma." (PMID 32709063, 2020).
papillary thyroid cancer (5 papers, 2018 to 2025). "Beyond chemoresistance, ATAD2 contributes to tumor progression and immune evasion; for instance, in papillary thyroid cancer (PTC), it promotes oncogenic behaviors by activating the PI3K-AKT pathway and regulating the G1/S cell cycle transition." (PMID 41154392, 2025). "For instance, NEAT1 was considered to be a competing endogenous RNA to modulate the expression of ATAD2 by suppressing miR-106b-5p in papillary thyroid cancer." (PMID 30053878, 2018). "In addition, NEAT1 was found to promote papillary thyroid cancer through regulating ATAD2 expression by sponging miR-106b-5p31." (PMID 30154460, 2018). "Another long noncoding RNA (lncRNA)-NEAT1_2, is highly upregulated in papillary thyroid carcinoma (PTC) and promotes the expression of ATAD2, which aids in the growth and spread of the tumor." (PMID 41154392, 2025).
retinoblastoma (5 papers, 2020 to 2023). A malignant tumor that originates in the nuclear layer of the retina. "Over-expression of miR-186 can reduce the expression of ATAD2, inhibit the Hedgehog signaling pathway and ultimately inhibit the proliferation, migration, invasion and apoptosis of retinoblastoma cells." (PMID 36632213, 2023). "MiR-186 further inactivates the Hedgehog signaling pathway by targeting ATAD2 in retinoblastoma cells, thereby inhibiting cell viability, migration, and angiogenesis." (PMID 36139505, 2022). "ATAD2 is highly expressed and directly negatively regulated by miR-186 in retinoblastoma (RB)." (PMID 36008934, 2022).
breast tumors (4 papers, 2019 to 2024). "The mRNA expression of ATAD2 was increased in 24 human breast tumor tissues compared to that in normal samples." (PMID 36139505, 2022). "ATAD2 mRNA expression was approximately 4-fold higher in breast tumor tissues than in normal tissues." (PMID 36139505, 2022). "Analysis of TCGA RNA sequencing data through the UALCAN platform revealed that the expression of ATAD2, E2F1, and FOXM1 were all significantly higher in primary breast tumor samples when compared to normal samples." (PMID 39335162, 2024). "Even though the fold change of BCAS4 was less than the other three up-regulated proteins (periostin, ATAD2, and Ki-67), it was still attractive because BCAS4 was significantly increased in breast tumors compared to normal tumors reported by UALCAN." (PMID 37922300, 2023). "Other identified gene was ATAD2, which has been previously implicated in the transcription regulation of genes by the ER24,25; although no data exist in HER2 positive breast tumors." (PMID 30952871, 2019).
oral squamous cell carcinoma (4 papers, 2020 to 2025). "Furthermore, by observing the effect of ATAD2 gene silencing on the proliferation and migration of tumor cells, the relationship between ATAD2 and the occurrence, development and metastasis of oral squamous cell carcinoma was revealed." (PMID 32669963, 2020). "However, the expression of ATAD2 and its related mechanism in oral squamous cell carcinoma (OSCC) are still unknown." (PMID 32669963, 2020). "ATAD2 overexpression was associated significantly with the expression of PD-L1, B7-H4, ALDH1, Slug, and CMTM6 proteins in oral squamous cell carcinoma (OSCC), suggesting that ATAD2 played an important function in the regulation of EMT, immunosuppression, and CSCs in OSCC." (PMID 36008934, 2022).
liver cancer (3 papers, 2014 to 2023). An epithelial or non-epithelial malignant neoplasm that arises from the liver. "Compared to the normal cell line LO2, Huh7 and HCCLM3 cells showed relatively higher levels of ATAD2 expression in seven liver cancer cell lines by Western blotting." (PMID 24552534, 2014). "Cell invasion and migration assays demonstrated that the Huh7 and HCCLM3 liver cancer cell lines that were transfected with ATAD2 siRNA displayed more attenuated invasive and migratory capacities than those of the negative controls." (PMID 24552534, 2014). "ATAD2 was highly expressed in liver cancer samples and correlated with poor survival." (PMID 24552534, 2014).
pancreatic cancer (3 papers, 2022 to 2023). "For instance, in pancreatic cancer, ATAD2 inhibition increases the sensitivity of pancreatic cancer cells to gemcitabine and radiotherapy." (PMID 36632213, 2023). "In addition, miR-217 has also been reported to bind to the 3'UTR site, inhibit ATAD2 protein expression and induce apoptosis of pancreatic cancer cells." (PMID 36632213, 2023). "ATAD2 deletion inhibited the invasive and migratory functions of pancreatic cancer cells (PCCs) and made them susceptible to gemcitabine, and ATAD2 gene knockout inhibited the non-anchored growth of PCCs in vitro." (PMID 36008934, 2022). "The results indicate that ATAD2 is responsible for the malignant features of pancreatic cancer." (PMID 36008934, 2022). "During, miR-217 blocked pancreatic cancer progression by inactivating the AKT pathway, which may be partly due to miR-217 mediated inhibition of ATAD2 expression, but further studies are needed." (PMID 36008934, 2022).
renal carcinoma (3 papers, 2011 to 2023). A carcinoma arising from the epithelium of the renal parenchyma or the renal pelvis. "ATAD2 was investigated to be highly expressed in renal cancer, and ATAD2 serves as a target of miR-372 directly in renal cancer cell lines and is regulated negatively by miR-372, which in turn affects cancer cell invasion, metastasis, and EMT function." (PMID 36008934, 2022). "ATAD2 is an attractive biomarker and therapeutic target for renal cancer." (PMID 36008934, 2022).
clear cell renal cell carcinoma (2 papers, 2023 to 2024). "Notably, the degradation of ATAD2 protein was observed in cell lines harboring mutant VHL, like clear cell renal cell carcinoma-derived cell lines, RCC4 and 786-O, upon hypoxic treatment, indicating that the regulation of ATAD2 protein was independent of the pVHL–HIF axis and its downstream genes." (PMID 38730681, 2024).
endometrial tumor (2 papers, 2022 to 2024). "ATPase Family AAA Domain Containing 2 (ATAD2) is frequently expressed in breast, lung, colorectal, liver, gastric, oral, ovarian, cervical, and endometrial tumors, and correlates with disease severity and poor prognosis." (PMID 38596293, 2024).
glioma (2 papers, 2017 to 2026). A benign or malignant brain and spinal cord tumor that arises from glial cells (astrocytes, oligodendrocytes, ependymal cells). "In conclusion, our study presents a comprehensive analysis of the CTA-related risk model and the druggable protein ATAD2 in gliomas." (PMID 41158756, 2026). "While current research on ATAD2 has primarily focused on other tumor types, its expression patterns, functional roles, and regulatory mechanisms in glioma remain poorly understood." (PMID 41158756, 2026). "In summary, our findings collectively demonstrate that ATAD2 promotes malignant progression in glioma and synergistically up-regulates PDK1 expression in cooperation with E2F1." (PMID 41158756, 2026). "Given that ATAD2 functions as a transcriptional coactivator, it is possible that ATAD2 synergizes with other transcription factors in glioma." (PMID 41158756, 2026). "Analysis of ATAD2 mRNA and protein expression was carried out to compare glioma tissues with normal brain tissues." (PMID 41158756, 2026). "Collectively, these findings suggest that ATAD2 can regulate the expression of multiple metabolism-related proteins, indicating its potentially significant impact on the metabolic pathways in glioma." (PMID 41158756, 2026). "Collectively, these results highlight the role of ATAD2 in promoting glioma progression." (PMID 41158756, 2026). "While several CTAs have been associated with the development and progression of gliomas, the role of ATPase family AAA domain-containing protein 2 (ATAD2) in this context has not been thoroughly investigated." (PMID 41158756, 2026). "However, the interplay between ATAD2 and E2F1 in regulating PDK1 expression in glioma is not yet fully understood." (PMID 41158756, 2026).
-dependent (1 paper, 2023). "Due to the fact that ATAD2 is a co-activator of the ERs and the androgen receptors in BC, it mediates the expression of E2 that induces cell proliferation and cell cycle progression in estrogen-dependent tumors." (PMID 37922300, 2023).
aortic stenosis (1 paper, 2025). Aortic valve stenosis is a aortic valve disease caused by the incomplete opening of the aortic valve. "In heart tissue biopsies from patients with aortic stenosis, TCF19 and ATAD2 abundance were positively correlated with endothelial cell proliferation." (PMID 40962957, 2025). "To validate these findings in human heart tissue, we assessed the abundance of ATAD2 and TCF19 in left ventricular biopsies from patients with aortic stenosis (n = 7)." (PMID 40962957, 2025).
cardiac hypertrophy (1 paper, 2025). "In conclusion, we found an association of TCF19 and ATAD2 expression with endothelial cell proliferation during cardiac hypertrophy in mice and humans." (PMID 40962957, 2025). "Downregulation of TCF19 and ATAD2 is associated with endothelial cell cycle arrest and an impaired angiogenic response to VEGF signaling that may promote the transition from compensated cardiac hypertrophy to heart failure." (PMID 40962957, 2025).
colon cancer (1 paper, 2025). "In addition, downregulation of ATAD2 in colon cancer cell lines suppressed VEGF secretion." (PMID 40962957, 2025).
dysplasia (1 paper, 2020). A usually neoplastic transformation of the cell, associated with altered architectural tissue patterns. "Remarkably, the staining intensity of ATAD2 was found to be much stronger in OSCC (n = 176) than in dysplasia (n = 69, p < 0.001) and normal oral mucosa (n = 42, p < 0.001)." (PMID 32669963, 2020).
endometrioid tumor (1 paper, 2015). A benign, borderline, or malignant epithelial tumor of the female reproductive system characterized by the presence of glands and/or cysts lined by neoplastic cells that resemble endometrial cells. "We find ATAD2 to be an independent prognostic marker in endometrioid tumors and high ATAD2 corresponds with aggressive disease for ERα positive patients." (PMID 26308378, 2015).
head and neck squamous cell carcinoma (1 paper, 2020). A squamous cell carcinoma that arises from any of the following anatomic sites: lip and oral cavity, nasal cavity, paranasal sinuses, pharynx, larynx, and salivary glands. "Moreover, the results from GEPIA (gene expression profiling interactive analysis, gepia.cancer-pku.cn) indicated a significant difference in ATAD2 mRNA expression, with higher expression in head and neck squamous cell carcinoma (HNSCC) than in normal mucosa (p < 0.05)." (PMID 32669963, 2020).
heart failure (1 paper, 2025). Inability of the heart to pump blood at an adequate rate to meet tissue metabolic requirements. "Thus, we conclude that TCF19 and ATAD2 control a gene expression network involved in endothelial cell proliferation and angiogenesis and their downregulation is linked to the cell cycle arrest observed at the transition to heart failure." (PMID 40962957, 2025). "Further studies are needed to identify signaling cascades that lead to the downregulation of TCF19 and ATAD2 in heart failure." (PMID 40962957, 2025). "In contrast, no significant regulation could be found after experimental myocardial infarction, indicating that the regulation of Tcf19 and Atad2 may be specific for heart failure with more pronounced cardiac myocyte hypertrophy." (PMID 40962957, 2025). "From a translational point of view, therapeutic restoration of TCF19 and ATAD2 expression could improve the angiogenic capacity of endothelial cells in the heart and provide benefit for patients with heart failure." (PMID 40962957, 2025).
nasopharyngeal carcinoma (1 paper, 2022). A carcinoma arising from the nasopharyngeal epithelium. "ATAD2 may be involved in the occurrence of nasopharyngeal carcinoma (NPC) by regulating the cell cycle and nucleic acid metabolism process, and it is also a molecular biomarker for the early diagnosis of NPC." (PMID 36008934, 2022).
neuroblastoma (1 paper, 2023). Neuroblastoma (NB) is the most common solid, extracranial childhood tumor. "The mRNA content was determined using several multiplex droplet digital PCR (ddPCR) assays for a neuroblastoma-specific gene panel (PHOX2B, TH, CHRNA3) and a cell cycle regulation panel (E2F1, CDC6, ATAD2, H2AFZ, MCM2, DHFR)." (PMID 37046768, 2023).
ovarian tumors (1 paper, 2024). "Except for ATAD2, expression of other genes (ASF1B, CCNE1, CDC20, CDCA8, RECQL4, RNASEH2A, and SMC4) was upregulated in ovarian tumors compared to non-cancerous tissue." (PMID 39199556, 2024).
Pan (1 paper, 2020). "ATAD2 had the highest Pan-Cancer Driver score, showing all the SNA, CNA, and expression Z-score alterations in many cancer types." (PMID 32963031, 2020).
parathyroid adenomas (1 paper, 2019). "Among those genes up-regulated in parathyroid adenomas, some, such as MED12, KMT5A, BMP2K, and ATAD2, are implicated in cell proliferation and transcriptional regulation, supporting the notion that they potentially contribute to tumorigenesis." (PMID 30832348, 2019).
parathyroid tumor (1 paper, 2019). "We speculate that ATAD2 could link E2F and MYC pathways and contribute to parathyroid tumor development." (PMID 30832348, 2019).
prostate tumors (1 paper, 2022). "As a direct binding partner for both E2F and c‐Myc, ATAD2 induces the expression of genes that facilitate cell cycle progression and inhibition of apoptosis in many different types of cancers, including breast, lung and prostate tumors." (PMID 35049055, 2022).
psoriasis (1 paper, 2025). An autoimmune condition characterized by red, well-delineated plaques with silvery scales that are usually on the extensor surfaces and scalp. "Additionally, aspirin has been shown to inhibit ESCC progression by downregulating the ATAD2/KIF4A axis; while etoposide ameliorates psoriasis and Crohn’s comorbidity by regulating KIF4A." (PMID 41361459, 2025).
serous ovarian cancer (1 paper, 2024). "Additionally, the Kaplan–Meier plot results revealed that increased expression of ATAD2, CCNE1, CDC20, and SMC4 was associated with poor survival in serous ovarian cancer patients (p < 0.05)." (PMID 39199556, 2024).
tongue cancer (1 paper, 2025). A malignant neoplasm affecting the tongue. "Among these, four genes (LY6K, ATAD2, CEP55, and MAGEA3) emerged as the most predictive of nodal spread specifically in tongue cancer." (PMID 41009820, 2025).
triple-negative breast carcinoma (1 paper, 2023). An invasive breast carcinoma which is negative for expression of estrogen receptor (ER), progesterone receptor (PR), and human epidermal growth factor receptor 2 (HER2). "Collectively, these results provide new enlightenment for the development of novel potent ATAD2 inhibitors for triple-negative breast cancer (TNBC) treatment." (PMID 37533352, 2023).
virus infection (1 paper, 2024). "LOC113841329 is predicted to be a homologue of the ATAD2 bromodomain, which is a small protein module that recognizes acetylated lysine on histones, thereby connecting to many diseases, including cancer, inflammation, and viral infection." (PMID 39408741, 2024). "Thus, inhibition of LOC113841329/ATAD2 may suppress progression of tumor or virus infection." (PMID 39408741, 2024).